SLC25A27 (solute carrier family 25 member 27)
Description:
Facilitates proton transport across the inner mitochondrial membrane and may dissipate excessive proton gradient associated with oxidative and metabolic stress at neuronal synapses. Regulates glutamate-induced proton conductance in astrocytes, shifting the energy metabolism toward aerobic glycolysis and lactate transfer to neurons for ATP synthesis. Can transport chloride ions with lower efficiency. The transport mechanism remains to be elucidated.
Synonyms: UCP4; FLJ33552
Tractability: Antibody: UniProt predicts a signal peptide or a membrane-spanning region. PROTAC: its protein half-life has been measured.
Gene: Protein-coding gene on chromosome 6 (46,652,915 to 46,678,190, forward strand). Ensembl gene ENSG00000153291.
Subcellular location: Mitochondrion inner membrane
Subcellular location (Human Protein Atlas): Mitochondria
Pathways (Reactome):
Metabolism: The fatty acid cycling model
Gene Ontology:
Molecular function: chloride transmembrane transporter activity; protein homodimerization activity; proton transmembrane transporter activity
Biological process: response to cold; chloride transmembrane transport; inner ear development; intracellular triglyceride homeostasis; negative regulation of apoptotic process; negative regulation of mitochondrial calcium ion concentration; negative regulation of mitochondrial membrane potential; positive regulation of cell population proliferation; proton transmembrane transport; regulation of D-glucose import
Cellular component: mitochondrial inner membrane; mitochondrial membrane; mitochondrion; apical part of cell; neuronal cell body
Genetic constraint (gnomAD): Loss-of-function variants: 16 observed, 22.41 expected, observed/expected ratio (o/e) 0.71, 90% interval 0.48 to 1.08. The upper end of that interval is the gene's LOEUF score, 1.08, which puts it in group 4 of 6, group 1 being the genes least tolerant of losing a copy. Missense variants: 186 observed, 213.76 expected, observed/expected ratio (o/e) 0.87, 90% interval 0.77 to 0.98. Synonymous variants: 79 observed, 76.79 expected, observed/expected ratio (o/e) 1.03, 90% interval 0.86 to 1.24.
Homologues: Orthologues: chimpanzee SLC25A27 (99% identical), macaque SLC25A27 (99% identical), rabbit SLC25A27 (98% identical), mouse Slc25a27 (95% identical), guinea pig SLC25A27 (94% identical), rat Slc25a27 (94% identical), dog SLC25A27 (90% identical), pig SLC25A27 (89% identical), tropical clawed frog slc25a27 (72% identical), zebrafish slc25a27 (67% identical), Drosophila melanogaster Ucp4A (55% identical), Caenorhabditis elegans ucp-4 (48% identical), and 2 more. Paralogues in human: SLC25A14 (37% identical), SLC25A30 (37% identical), UCP3 (33% identical), UCP2 (32% identical), UCP1 (28% identical), SLC25A12 (26% identical), SLC25A13 (26% identical), SLC25A31 (24% identical), SLC25A35 (23% identical), SLC25A34 (23% identical), SLC25A4 (23% identical), SLC25A38 (23% identical), and 37 more.
Diseases named in the same sentence as SLC25A27 in open-access papers:
SLC25A27 is named in the same sentence as 32 diseases in open-access papers, as found by Europe PMC text mining. Sharing a sentence is not in itself a finding about the gene and the disease. The quoted sentences say what the papers report.
Alzheimer disease (7 papers, 2011 to 2024). A progressive, neurodegenerative disease characterized by loss of function and death of nerve cells in several areas of the brain leading to loss of cognitive function such as memory and language. "These authors identified an intronic variant of the neuronal UCP4 (UCP4/SLC25A27) gene that affects the risk of late-onset Alzheimer’s disease (LOAD) and late-onset familial and sporadic cases of frontotemporal dementia." (PMID 31366145, 2019). "We recently reported that rs9472817-C/G, an intronic variant of neuronal mitochondrial uncoupling protein-4 (UCP4/SLC25A27) gene affects the risk of late onset Alzheimer's disease (LOAD), and that the variant's effect is strongly dependent on APOE-ε4 status." (PMID 30425186, 2018). "Additionally, SLC25A27 contributes to long chain fatty acid uptake and controls several diseases in humans, such as Alzheimer’s disease, oxidative stress, and fasting." (PMID 31665138, 2019).
schizophrenia (5 papers, 2012 to 2024). A major psychotic disorder characterized by abnormalities in the perception or expression of reality. "Association of an UCP4 (SLC25A27) haplotype with ultra-resistant schizophrenia." (PMID 30093869, 2018). "Association of a UCP4 (SLC25A27) haplotype with ultraresistant schizophrenia." (PMID 22950050, 2012). "In addition, SLC25A27 might play neuroprotective roles in the developing brain cortex, and its gene is associated with the treatment-resistant form of schizophrenia, a neurodevelopmental disorder." (PMID 36551763, 2022).
autism (4 papers, 2012 to 2021). Persistent deficits in social interaction and communication and interaction as well as a markedly restricted repertoire of activity and interest as well as repetitive patterns of behavior. "NEFL (P = 0.038; Z-score 2.066) and SLC25A27 (P = 0.046; Z-score 1.990) showed genetic association with autism in Caucasian and Japanese samples, respectively." (PMID 23116158, 2012). "We observed a nominal association of SLC25A27 with autism in Japanese samples." (PMID 23116158, 2012). "We observed only nominal association of NEFL and SLC25A27 with autism." (PMID 23116158, 2012). "SLC25A27 showed a nominal association with autism in Japanese samples." (PMID 23116158, 2012). "We also observed nominal genetic association of NEFL and SLC25A27 with autism." (PMID 23116158, 2012). "NEFL, SLC25A27 and MTX2 showed reduced expression in all the three brain regions of autism patients." (PMID 23116158, 2012). "Metaxin 2 (MTX2), neurofilament, light polypeptide (NEFL) and solute carrier family 25, member 27 (SLC25A27) showed consistently reduced expression in the ACG, MC and THL of autism patients." (PMID 23116158, 2012). "MTX2, NEFL and SLC25A27 showed consistently reduced expression in the ACG, MC and THL of autism patients." (PMID 23116158, 2012).
breast carcinoma (1 paper, 2022). "SLC25A27 (a.k.a Uncoupling Protein 4, UCP4), which, uncouples oxidation of substrates from ADP phosphorylation in mitochondria by modulating membrane potential, is a prognostic marker in breast cancer." (PMID 37529795, 2022).
breast invasive cancer (1 paper, 2022). "Moreover, SLC25A7 and SLC25A27 had decreased expression in breast invasive cancer while SLC25A41 was increased." (PMID 36254139, 2022).
lung squamous cell carcinoma (1 paper, 2022). "In lung squamous cell carcinoma, SLC25A27 and SLC25A25 were reduced." (PMID 36254139, 2022).
uterine corpus endometrial carcinoma (1 paper, 2022). A endometrial carcinoma (disease) that involves the body of uterus. "In uterine corpus endometrial carcinoma, the mutation of SLC25A4, SLC25A25, and SLC25A27 had certain impacts on their expression." (PMID 36254139, 2022).
cancer (8 papers, 2014 to 2025). A tumor composed of atypical neoplastic, often pleomorphic cells that invade other tissues. "While UCP1, UCP3, SLC25A27, and SLC25A14 were frequently downregulated in most cancers, UCP2 showed consistent upregulation, indicating divergent functional roles in oncogenesis." (PMID 41403699, 2025). "These consistent expression patterns suggest that UCP2 may function as an oncogene in diverse cancer contexts, while UCP1, UCP3, SLC25A27, and SLC25A14 are potentially involved in tumor-suppressive mechanisms." (PMID 41403699, 2025).
tumor (6 papers, 2014 to 2025). "The expression levels of IGF2BP2, RAI2, SLC25A27, NCBP2, and EIF4B were greatly enhanced, as is the case in tumor development." (PMID 25978455, 2015). "UCP1, UCP3, SLC25A27, and SLC25A14 showed significantly lower expression in most tumor tissues." (PMID 41403699, 2025). "The expression level of SLC25A27 was positively correlated with tumor purity and the infiltration levels of CD4+ T cells, but not with the infiltration levels of CD8+ T cells, dendritic cells, B cells, macrophages, and neutrophil." (PMID 34868460, 2021). "Conversely, the frequent downregulation of other UCP family members, such as UCP3 and SLC25A27, across tumors suggests their potential roles as tumor suppressors, although this remains speculative without functional validation." (PMID 41403699, 2025).
SLC25A27 also shares sentences with these, for which no sentence is quoted: neuroblastoma (7 papers); neurodegenerative disease (6); frontotemporal dementia (3); leukoaraiosis (3); multiple sclerosis (3); Parkinson disease (3); autism spectrum disorder (2); Bradykinesia (1); depression (1); diabetes (1); Huntington disease (1); Hypertension (1); hypothyroidism (1); leukemia (1); lung adenocarcinoma (1); lung carcinoma (1); neurodevelopmental disorder (1); neurological disorders (1); nonalcoholic fatty liver disease (1); Onset (1); ovarian carcinoma (1); Parkinsonism (1); prostate carcinoma (1).